CCNE2 (cyclin E2)
Description:
Essential for the control of the cell cycle at the late G1 and early S phase.
Synonyms: CYCE2
Tractability: Small molecule: a structure with a bound ligand is known; a high-quality ligand is known; it belongs to a druggable protein family. PROTAC: ubiquitination databases record sites on it; a small molecule that binds it is known.
Gene: Protein-coding gene on chromosome 8 (94,879,641 to 94,896,678, reverse strand). Ensembl gene ENSG00000175305.
Subcellular location: Nucleus
Pathways (Reactome):
Cell Cycle: Cyclin D associated events in G1; Cyclin E associated events during G1/S transition; G0 and Early G1; Phosphorylation of proteins involved in G1/S transition by active Cyclin E:Cdk2 complexes; SCF(Skp2)-mediated degradation of p27/p21
Cellular responses to stimuli: DNA Damage/Telomere Stress Induced Senescence
DNA Replication: CDK-mediated phosphorylation and removal of Cdc6
Disease: Defective binding of RB1 mutants to E2F1,(E2F2, E2F3)
Metabolism of proteins: Association of TriC/CCT with target proteins during biosynthesis
Gene Ontology:
Molecular function: protein binding; cyclin-dependent protein serine/threonine kinase regulator activity; protein kinase binding
Biological process: G1/S transition of mitotic cell cycle; positive regulation of G1/S transition of mitotic cell cycle; regulation of cyclin-dependent protein serine/threonine kinase activity
Cellular component: cyclin E2-CDK2 complex; nucleus; cyclin E1-CDK2 complex; cytosol; microtubule organizing center; nucleoplasm
Genetic constraint (gnomAD): Loss-of-function variants: 9 observed, 29.26 expected, observed/expected ratio (o/e) 0.31, 90% interval 0.18 to 0.54. The upper end of that interval is the gene's LOEUF score, 0.54, which puts it in group 2 of 6, group 1 being the genes least tolerant of losing a copy. Missense variants: 183 observed, 229.06 expected, observed/expected ratio (o/e) 0.8, 90% interval 0.71 to 0.9. Synonymous variants: 72 observed, 72.61 expected, observed/expected ratio (o/e) 0.99, 90% interval 0.82 to 1.21.
Homologues: Orthologues: chimpanzee CCNE2 (99% identical), macaque CCNE2 (99% identical), pig CCNE2 (96% identical), rabbit CCNE2 (95% identical), dog CCNE2 (95% identical), rat Ccne2 (93% identical), mouse Ccne2 (92% identical), tropical clawed frog ccne2 (63% identical), zebrafish ccne2 (59% identical), Drosophila melanogaster CycE (41% identical), Caenorhabditis elegans cya-1 (22% identical), Caenorhabditis elegans cye-1 (22% identical), and 9 more. Paralogues in human: CCNE1 (48% identical), CCNB1 (23% identical), CCNB2 (22% identical), CCNA1 (21% identical), CCNA2 (20% identical), CCNB3 (19% identical), CCNF (18% identical), CCNI (17% identical), CCND1 (16% identical), CCND3 (16% identical), CCNO (16% identical), CCND2 (16% identical), and 6 more.
Diseases named in the same sentence as CCNE2 in open-access papers:
CCNE2 is named in the same sentence as 84 diseases in open-access papers, as found by Europe PMC text mining. Sharing a sentence is not in itself a finding about the gene and the disease. The quoted sentences say what the papers report.
breast carcinoma (70 papers, 2008 to 2026). "To investigate the relationship between CCNE2 and genomic stability, we first comprehensively analyzed the mutation landscape in breast cancer patients using the R package “maftools”." (PMID 36233194, 2022). "Overexpression of CCNE2 has been associated with pathogenesis, endocrine resistance, metastasis, and reduced survival in breast cancer." (PMID 35200555, 2022). "We show that both cyclin E1 (CCNE1) and cyclin E2 (CCNE2) mRNA are significantly associated with high genome ploidy in breast cancers." (PMID 32823571, 2020). "Low CCNE2 is associated with improved overall survival in breast cancers, and we demonstrate that low cyclin E2 protects from excess genome rereplication." (PMID 32823571, 2020). "Inactivation of PPP1CB caused chronic lymphocytic leukemia, whereas CCNE2 was related to the development of non-small cell lung cancer and breast cancer." (PMID 26308735, 2015). "In 526 breast cancers, high CCNE2 expression is associated with high levels of replication-dependent histones that are under the control of NPAT." (PMID 25741376, 2015). "Cyclin E2 has a strong prognostic role in breast cancer, and induces genomic instability that is associated with defects in chromosome condensation." (PMID 25741376, 2015). "Both CCNE1 and CCNE2 are expressed at higher levels in breast cancer, with an association of both genes to increased tumour grade, estrogen receptor (ER) negative status, progesterone receptor negative status, and proliferative index by Ki67 staining." (PMID 20180967, 2010). "Anti-estrogen resistance in MCF-7 breast cancer cells conferred by the TNFα inhibitor, A20, is also associated with increases in cyclin E2 expression." (PMID 20180967, 2010). "Thus, in breast cancer, cyclin E2 has a strong association with genome doubling, and likely contributes to highly proliferative and genomically unstable breast cancers." (PMID 32823571, 2020). "Cyclin E2 (CCNE2) is involved in the cell cycle G1/S transition and it has been reported that the overexpression of CCNE2 is associated with endocrine resistance in human breast cancer cells." (PMID 25955318, 2015). "Indeed, PTEN downregulation and AKT increased phosphorylation were shown to be associated with increased CDK2/cyclin E2 expression in breast cancer cell lines resistant to CDKi, rendering PI3K inhibitors (capable of downregulating cyclin E2) an attractive partner to overcome resistance to CDKi." (PMID 36741019, 2023). "CCNE2 may be a candidate risk indicator of breast cancer in women using MHT." (PMID 36233194, 2022). "CCNE2, an S phase cyclin is frequently overexpressed in breast cancer with previous studies reported the overexpression of Cyclin E including CCNE2 in IBC, with correlation of poor prognosis in IBC patients." (PMID 41427337, 2025). "In a recent study, using RT-qPCR, two panels of transcripts related to the presence of CTCs (Panel 1: CK19, EpCAM, SCGB2A2 and Panel 2: EMP2, SLC6A8, HJURP, MAL2, PPIC and CCNE2), in two cohorts of breast cancer patients (metastatic and early), were evaluated." (PMID 37046848, 2023). "KCNQ1OT1 is found to be remarkably high expression in breast cancer tissues and cells, which promoted tumor growth in vivo by regulatingmiR-145/CCNE2." (PMID 34983363, 2022). "Overexpression of CCNE2 has been found in various types of cancer, such as breast cancer and lung cancer." (PMID 36233194, 2022).
breast carcinoma (continued). "Kcnq1ot1 was upregulated and modulated cyclin E2 (CCNE2) in breast cancer tissues and cells through sponging miR-145." (PMID 35328609, 2022). "Therefore, CCNE2 might be linked to genomic stability in breast cancer." (PMID 36233194, 2022). "To further corroborate the role of cyclin E in resistance to fulvestrant, we analyzed the expression of cyclin E2 by IHC in metastatic tumor samples from a cohort of 83 ER+ breast cancer patients treated with fulvestrant." (PMID 33602273, 2021). "Further from this, we saw the same pattern of cyclin E2 upregulation upon development of resistance to fulvestrant in two out of three metastatic breast cancer patients with paired biopsies before and after fulvestrant treatment." (PMID 33602273, 2021). "In breast cancer, cyclin E2 shows a greater prognostic value, including being part of gene signatures that predict disease progression in metastatic breast cancer, whereas cyclin E1 is absent from these same signatures." (PMID 32823571, 2020). "This led us to question if CCNE1 and CCNE2 have similar relationships with proliferation and genome instability in breast cancer." (PMID 32823571, 2020). "Overall, our data demonstrate that both cyclins E1 and E2 predict overall survival in non-genome doubled cancers, but the high expression of cyclin E1 or cyclin E2 is likely to provoke different events in the evolution of breast cancer." (PMID 32823571, 2020). "We first determined how cyclin E1 and cyclin E2 related to genome ploidy by examining the relationship between the expression of the cyclins E1 and E2 genes, CCNE1 and CCNE2, and the genome doubling status of TCGA breast cancers (n = 831)." (PMID 32823571, 2020). "CCNE2 is almost undetectable in normal breast cells, and it is significantly upregulated in breast cancer cells." (PMID 32487779, 2020). "CCNE1 gene amplification is rare in breast cancer (3.4%), whereas CCNE2 gene amplification occurs in 16.4% of breast cancers." (PMID 32823571, 2020). "This is also consistent with the frequent presence of CCNE2 in gene signatures of breast cancer metastasis, as metastatic cancers have a higher frequency of genome doubling." (PMID 32823571, 2020). "This suggests that cyclin E2 induces DNA rereplication when overexpressed in T-47D breast cancer cells." (PMID 32823571, 2020). "Cyclin E2 is a canonical E2F target gene, especially in breast cancer, and its overexpression is able to overcome G1 arrest in this setting." (PMID 32823571, 2020). "Evaluating the expression of cell cycle proteins showed that cyclin D1 and cyclin E2 were significantly induced in breast cancer cells in which TAP was knocked down." (PMID 29435127, 2018). "Looking at the biological functions of CCNE2, HPSE, and PFKM proteins, they are for the most part, involved in cell cycle G1/S transition, proliferation and carcinogenesis, and associated with breast cancer." (PMID 28505145, 2017). "For example, cyclin E2 is the major E-cyclin within HLBs in breast cancer cells and has a strong prognostic role in breast cancer." (PMID 29212286, 2017). "Collectively, these results demonstrate that E2F8 can upregulate cyclin E1 and cyclin E2 in breast cancer by binding to the promoter of the CCNE1 and CCNE2 genes to activate their transcription." (PMID 26992224, 2016). "As expected, luciferase reporter assays revealed that overexpression of E2F8 activated, whereas downregulation of E2F8 attenuated, the luciferase activity of CCNE1 and CCNE2 promoters in breast cancer cells in a dose-dependent manner." (PMID 26992224, 2016). "We further demonstrate that E2F8 transcriptionally upregulates CCNE1 and CCNE2 via directly interacting with their respective gene promoter, which accelerates the transition of G1 to S phase of breast cancer cells." (PMID 26992224, 2016).
breast carcinoma (continued). "E2F8 levels in 10 freshly collected breast cancer samples were significantly positively correlated with levels of cyclin E1 (r = 0.723, P = 0.018), cyclin E2 (r = 0.803, P = 0.005), and phosphorylation level of Rb (r = 0.639, P = 0.047)." (PMID 26992224, 2016). "Among those genes, we found that CCNE2 acts downstream of HMGA1 to mediate breast cancer metastasis." (PMID 26265440, 2015). "Our re-examination of cyclin E function has identified that cyclin E2 is likely to have particular role in histone regulation in breast cancer via its unique interaction with NPAT." (PMID 25741376, 2015). "Silencing of HMGA1 using a specific siRNA caused significant down-regulation of CCNE2 expression at both the mRNA and protein levels in the MDA-MB-231 and MDA-MB-157 breast cancer cell lines." (PMID 26265440, 2015). "In breast cancer patients, high levels of HMGA1 and CCNE2 expression are associated with the YAP/TAZ signature, supporting this connection." (PMID 26265440, 2015). "Taken together, these results suggest that CCNE2 plays a specific role in promoting cell migration and invasion in metastatic breast cancer cell lines downstream of HMGA1." (PMID 26265440, 2015). "In this study, we investigated the contribution of HMGA1 and CCNE2 to breast cancer cell migration and invasion." (PMID 26265440, 2015). "Our study for the first time demonstrated that, stimulation of the hERG1 channel activity rapidly suppresses cyclin E2 in diverse breast cancers cell lines including Trastuzumab-resistant cells." (PMID 25596745, 2015). "Our laboratory has previously reported that stimulation of the hERG1 potassium channel with selective activators led to down-regulation of cyclin E2 in breast cancer cells." (PMID 25596745, 2015). "Altogether, our findings strongly suggest that stimulation of the hERG1 potassium channels in breast cancer cells induces a calcium-dependent degradation of cyclin E2 via activation of an ubiquitin-dependent proteasome pathway." (PMID 25596745, 2015). "In conclusion, our study describes an unprecedented mechanism of cyclin E2 degradation in breast cancer cells which contributes to understanding of an important role of cyclin E2 in breast cancer biology." (PMID 25596745, 2015). "Knocking down cyclin E2 by its siRNA strongly inhibited proliferation in SKBr3 breast cancer cells compared to wild type SKBr3 cells." (PMID 25596745, 2015). "Our observation of a specific NPAT-cyclin E2 interaction in breast cancer cell lines was supported by our findings of high expression of replication-dependent histones in breast cancers that have high expression of cyclin E2." (PMID 25741376, 2015). "For example, the levels of cyclin E2 was significantly elevated in human breast cancers, and decrease of cyclin E2 severely attenuates the estrogen-induced breast cancer cell proliferation." (PMID 26378658, 2015). "Cyclin E2 uniquely interacts with NPAT in breast cancer cells, and is associated with higher levels of histones in breast cancer." (PMID 25741376, 2015). "Together the immunofluorescence and PLA data indicate that cyclin E2 is the major E-cyclin within HLBs in breast cancer cells and is likely to have a particular role in coordinating the cell cycle with histone transcription." (PMID 25741376, 2015). "Next, we investigated the possible relationship between HMGA1 and CCNE2 expression in breast cancer patients." (PMID 26265440, 2015). "Using basal-like breast cancer cell lines, we demonstrated that CCNE2 is an important downstream factor of HMGA1 that mediates tumor aggressiveness." (PMID 26265440, 2015). "CCNE2 has been detected in various prognostic gene expression profiles that predict a shorter metastasis-free survival or relapse-free interval in breast cancer patients." (PMID 26265440, 2015). "Previous publications describe binding of “cyclin E” to NPAT, whereas we here identify that cyclin E2 is the major E-cyclin within HLBs in breast cancer cells." (PMID 25741376, 2015).
breast carcinoma (continued). "Kaplan-Meier survival analysis revealed that the expression of CCNE2 alone significantly correlated with clinical outcome in breast cancer patients." (PMID 26265440, 2015). "Despite the relevance of cyclin E2 to breast cancer biology, the vast majority of studies defining the regulatory mechanisms that control type-E cyclins has been dedicated only to cyclin E1." (PMID 25596745, 2015). "We have previously shown that, acute stimulation of hERG1 ion channels in breast cancer cells promotes reduction (60%) of cyclin E2 protein level, whereas chronic stimulation down-regulated other cell cycle regulators." (PMID 25596745, 2015). "In this work, we demonstrate that stimulation of hERG1 promotes an ubiquitin-proteasome-dependent degradation of cyclin E2 in multiple breast cancer cell lines representing Luminal A, HER2+ and Trastuzumab-resistant breast cancer cells." (PMID 25596745, 2015). "This is consistent with studies in estrogen-responsive breast cancer cell lines where cyclin E2 is a highly estrogen responsive target, whereas cyclin E1 is only marginally increased." (PMID 20180967, 2010). "CCNE1 and CCNE2 expression has been compared in breast cancer, where these studies are representative of the majority of studies on the relationship of CCNE1 to breast cancer." (PMID 20180967, 2010). "We have made a similar observation in the breast cancer cell line MCF-7 that cyclin E2 knockdown leads to an increase in cyclin E1 protein levels, although this is associated with decreased overall proliferation." (PMID 20180967, 2010). "While cyclin E1-Cdk2 and cyclin E2-Cdk2 kinase activities are increased in breast cancer compared to normal tissue, cyclin E1 and E2 expression and kinase activity are not essential for proliferation of all cancer cell types." (PMID 20180967, 2010). "A close examination of gene identities in the cell cycle pathway, the Amsterdam 70-gene signature, and the control breast cancer gene signature revealed that the Amsterdam signature only included one cell cycle gene (cyclin E2)." (PMID 18786252, 2008). "In ER− parental and palbociclib-resistant MDA-MB-468 (Rb-deficient) breast cancer cells, DDX also downregulated cyclin E2 and cyclin A2 and unexpectedly restored the presence of the cell cycle repressor Rb, which is an integral part of the cell cycle checkpoint inhibiting the progression past G1." (PMID 38473336, 2024). "The associations of the Panel 2 markers MAL2, EMP2, CCNE2 and HJURP with short OS may point to different biological characteristics of the enriched cells and warrant further studies in aggressive breast cancer subtypes." (PMID 36831613, 2023). "In our present study, we evaluated two panels of transcripts related with the presence of circulating tumor cells (CTCs) (Panel 1: CK19, EpCAM, SCGB2A2 and Panel 2: EMP2, SLC6A8, HJURP, MAL2, PPIC and CCNE2) in two cohorts of breast cancer patients (metastatic and early)." (PMID 36831613, 2023). "Starting with the observation that A3B expression is heterogeneous in cultured breast cancer cells, we show that A3B expression associates strongly with Cyclin B1 and not Cyclin E2 on a single-cell level in cell lines and clinical breast cancer specimens." (PMID 37190094, 2023). "We also found that CCNE2 expression was upregulated by EPT and attenuated by acolbifene, an estrogen receptor antagonist, in breast cancer cells, and the higher expression of CCNE2 correlated with the progress and poor overall survival in breast cancer patients." (PMID 36233194, 2022). "CCNE2 may be the key gene contributing to preexisting occult breast cancer progression under MHT treatments, especially in ER-positive patients." (PMID 36233194, 2022). "In addition, HMGA1 upregulates the expression of cyclin E2 (CCNE2) to alter Yap nuclear localization and downstream activity of the Hippo pathway and finally regulates the movement of basal-like breast cancer cells." (PMID 35864955, 2022).